ABTB3 (ankyrin repeat and BTB domain containing 3)
Description:
Cortical and hippocampal inhibitory interneuron-specific protein localized at glutamatergic (excitatory) synapses, where it supports cell type-specific synaptic function.
Synonyms: BTBD11; FLJ33957; ABTB2B
Tractability: Antibody: UniProt predicts a signal peptide or a membrane-spanning region. PROTAC: ubiquitination databases record sites on it.
Gene: Protein-coding gene on chromosome 12 (107,318,421 to 107,659,642, forward strand). Ensembl gene ENSG00000151136.
Subcellular location: Membrane
Subcellular location (Human Protein Atlas): Nucleoplasm; Cytosol
Gene Ontology:
Molecular function: PDZ domain binding; protein heterodimerization activity
Cellular component: nucleoplasm; glutamatergic synapse; membrane
Genetic constraint (gnomAD): Loss-of-function variants: 31 observed, 92.69 expected, observed/expected ratio (o/e) 0.33, 90% interval 0.25 to 0.45. The upper end of that interval is the gene's LOEUF score, 0.45, which puts it in group 1 of 6, group 1 being the genes least tolerant of losing a copy. Missense variants: 1,200 observed, 1,279.9 expected, observed/expected ratio (o/e) 0.94, 90% interval 0.89 to 0.98. Synonymous variants: 554 observed, 545.21 expected, observed/expected ratio (o/e) 1.02, 90% interval 0.95 to 1.09.
Homologues: Orthologues: chimpanzee ABTB3 (99% identical), macaque ABTB3 (99% identical), dog ABTB3 (99% identical), pig ABTB3 (98% identical), mouse Abtb3 (98% identical), rat Abtb3 (97% identical), rabbit ABTB3 (93% identical), guinea pig ABTB3 (89% identical), tropical clawed frog abtb3 (79% identical), zebrafish btbd11a (69% identical), zebrafish btbd11b (68% identical), Drosophila melanogaster lute (10% identical), and 3 more. Paralogues in human: ABTB2 (52% identical), KLHL11 (13% identical), BTBD2 (10% identical), BTBD6 (9% identical), BTBD1 (9% identical), BTBD3 (9% identical), BTBD9 (9% identical), SPOPL (8% identical), ABTB1 (8% identical), SPOP (7% identical), KBTBD4 (5% identical).
Diseases named in the same sentence as ABTB3 in open-access papers:
ABTB3 is named in the same sentence as 6 diseases in open-access papers, as found by Europe PMC text mining. Sharing a sentence is not in itself a finding about the gene and the disease. The quoted sentences say what the papers report.
alcohol dependence (1 paper, 2025). Physical and psychological dependence on alcohol. "In the research on excessive alcohol intake, it has been reported that ABTB3 gene expression is significantly upregulated, indicating that ABTB3 may be related to alcohol metabolism, especially in the state of alcoholism or alcohol dependence." (PMID 40564278, 2025).
ABTB3 also shares sentences with these, for which no sentence is quoted: alcoholism (1 paper); dwarfism (1); Hypertension (1); lung carcinoma (1); tumor (1).